TLR5 (toll like receptor 5)
Diseases named in the same sentence as TLR5 in open-access papers (continued):
Sharing a sentence is not in itself a finding about the gene and the disease.
infection (continued). "Together with the fact that TLR-5 is not expressed on CF macrophages, all these results allow to understand how infection sets in CF patients, notably for P. aeruginosa pathogen." (PMID 24098711, 2013). "We observed a significant inter-individual variability (especially for TLR5) but none of these TLR was found to be induced by the infection, nor differentially expressed between the resistant and susceptible fish." (PMID 22720048, 2012). "HEK293 control cells, which do not induce TLR-2 and TLR-5 expression during infection, only secreted cytokines in small amounts, in agreement with T4SS functions being absent." (PMID 21573018, 2011). "As a result, the expression of TLR2 and TLR10 experienced no obvious alterations during infection, and the expression of TLR5 and TLR6 increased slightly, whereas the expression of TLR4 was downregulated significantly, which were consistent with previous reports." (PMID 33414472, 2021). "Therefore, the role of TLR5 beyond the recognition of flagellin, specifically in infection with non-flagellated bacteria in teleosts, warrants further investigation." (PMID 34880856, 2021). "Only TLR2-/-TLR5-/-Unc93b13d/3d mice failed to express significant IL-10 after Δhly infection." (PMID 32634175, 2020). "Therefore, we speculated that the expressions of TLR5 and IL1R2 transcripts were increased under the infection of C. irritans and might be crucial for the innate immune response." (PMID 33281881, 2020). "The expression of the TLR3, TLR5, and TLR6 genes in the liver tissue of infected rhesus macaques was downregulated in the early phase of HEV1 Sar-55 and HEV3-JN83748 infections, while TLR3 gene expression was only upregulated at peak infection and declined during HEV3 infection." (PMID 32731452, 2020). "It is notable that earlier studies interpreted the TLR5-dependent and Dot/lcm-dependent responses as separate effects achieved at different multiplicities of infection rather than sequential events occurring during infection." (PMID 30619320, 2018). "In addition, TLR5 mRNA expression level was upregulated in the gastric epithelial cell line GES-1 during infection with spiral-shaped H. pylori, but not by the corresponding coccoid form." (PMID 25945326, 2015). "If flagellin monomers were not present in the eye during infection, this may explain why the absence of TLR5 did not significantly impact intraocular inflammation during infection." (PMID 24959742, 2014). "We found that in neutrophils without H. pylori infection, the expression of TLR5 increased significantly after 24 h culture, whereas infection with cagPAI+, cagPAI–, or the virB4– or virD4– mutant strain resulted in the significant inhibition of TLR5 expression." (PMID 23755130, 2014). "However, if flagellin monomers were not present in the eye during infection, the increased number of flagella present in swarming organisms would be irrelevant, and TLR5/flagellin interactions would still not be as important to the outcome of infection." (PMID 24959742, 2014). "In contrast, HEK293-TLR2 and HEK293-TLR5 cells were highly competent for inducing the secretion of IL-8 and TNF-α cytokines in a cagPAI-independent manner, suggesting that the expression of TLR-2 or TLR-5 has profoundly changed the capability to trigger pro-inflammatory signalling upon infection." (PMID 21573018, 2011). "KSHV primary infection, expression of numerous KSHV genes, and abnormal activation of immune response in KSHV-infected cells including the alternative complement system and Toll-like receptor 4 and 5 (TLR4 and TLR5) pathways could also trigger inflammation (21, 28, –, 31, 38, –, 40)." (PMID 38117084, 2024). "However, such a response may not occur during apical infection of differentiated intestinal monolayers as the host's flagellin receptor, TLR-5, is considered to be excluded from this surface in model systems." (PMID 17388785, 2007).
infection (continued). "However, in the same study, pharmacologic CFTR inhibition did not influence TLR5 expression in non-CF MDMs, suggesting that the loss of TLR5 in CF macrophages may be influenced indirectly by CFTR dysfunction, infection, or through structural changes not recapitulated by channel inhibition." (PMID 35887098, 2022). "No infected tlr5−/− KO mice developed CDI and all animals survived at day 2 post-infection regardless of the strain." (PMID 28607468, 2017). "Consistent with our observations, B. pseudomallei isolates failed to significantly increase TLR5 expression in both cell culture and BALB/c mice infection models." (PMID 22823543, 2012). "Both receptors cooperate to defend the host from infection: the absence of both TLR4 and TLR5 results in hypersusceptibility for lung infection in mice." (PMID 21901099, 2011).
tumor (142 papers, 2012 to 2026). "In contrast, blockade of TLR5 attenuated C5aR1 inhibition-regulated tumor suppression in association with a decrease in CD86 expression and glycolysis in macrophages." (PMID 38331868, 2024). "In Kaplan-Meier analysis, the patients with strong TLR5 expression had worse survival compared to the patients with negative or mild TLR5 expression, but the results were linked to other patient and tumour characteristics." (PMID 31238894, 2019). "Using a mouse xenograft model of human colon cancer, a study showed that deficiency of TLR5 is associated with increased tumor volume accompanied with a deregulation of tumor immune response." (PMID 28632155, 2017). "This study also revealed that increased TLR9 expression correlated with advanced tumor size, while high TLR5 expression was associated with a lower tumor grade." (PMID 25999952, 2015). "Recently, it was reported that toll‐like receptor 5 (TLR5) was associated with some kind of tumours, especially in TNBC, but whether it could be used as a non‐invasive monitoring target is not fully understood." (PMID 31576678, 2019). "Consequently, the suppressive activity of γδT cells is entirely dependent upon TLR5 signaling by commensal bacteria, so that γδ T cells in TLR5-deficient tumor-bearing mice paradoxically show protective activity." (PMID 25897427, 2015). "In addition, TLR5 is associated with decreased tumor cell proliferation, invasion, and metastasis." (PMID 36479129, 2022). "Mobilan is a recombinant adenoviral vector engineered for PCa immunotherapy that co-expresses human TLR5 and a secreted flagellin-based TLR5 agonist, stimulating innate immunity to suppress tumor growth." (PMID 41601666, 2026). "This system targets hypoxic tumour regions, where bacteria proliferate and release VvFlaB, thereby activating TLR5 in the immune cells." (PMID 40444793, 2025). "PEI, a cationic organic polymer, has been reported as a ligand for TLR4 and TLR5 and is known to enhance the immunogenicity of tumor vaccines." (PMID 40291558, 2025). "The combined action of LPS and exogenous FlaB activates TLR4 and TLR5 signaling pathways, inducing monocyte, macrophage, and neutrophil infiltration into the tumor microenvironment." (PMID 40528960, 2025). "ICD of tumor cells by the TLIF-PTT should has provided TAs for epitope expansion as well as DAMP signals cooperating with the flagellin-TLR5 signaling axis." (PMID 40118497, 2025). "Paradoxically, clinical analyses have demonstrated that elevated TLR5 expression in tumor tissues correlates with favorable survival outcomes, potentially due to its role in activating antitumor immunity through neutrophil recruitment." (PMID 40727252, 2025). "Components of tumor cell activate TLR5 signaling, leading to increased secretion of IL‐8 cytokines and promoting malignant development of tumors." (PMID 40727252, 2025). "The expression level of TLR5 has been strongly correlated with tumor aggressiveness and patient prognosis." (PMID 40497049, 2025). "We observed an increase in F4/80+CD80+ macrophages in the tumor and spleen from the TLR5 agonist monotherapy and combination therapy groups." (PMID 38630304, 2024). "In xenograft and syngeneic mouse models of this cancer type, TLR5 signaling activation via TLR5 agonists can initiate innate immunity and elicit potent anti-tumor responses that regulate tumor growth." (PMID 38630304, 2024). "The expression and prognosis of TLR5 in different tumor diseases are different, and the use of agonists or antagonists remains to be further explored." (PMID 38685971, 2024). "Intriguingly, combination therapy involving the TLR5 agonist and anti-PD-1 exhibited a synergistic enhancement in the inhibitory effect on tumor growth." (PMID 38630304, 2024). "Another exciting study employed engineered T cells expressing the proinflammatory toll-like receptor-5 (TLR-5) agonist, flagellin, to modify the immunogenic “cold” tumor phenotype." (PMID 38333212, 2024).
tumor (continued). "We assessed the potential of TLR5 agonists and anti-PD-1 as monotherapies or combination therapy to suppress tumor growth." (PMID 38630304, 2024). "We examined the cytotoxicity effects of splenocytes against the target CT-26 tumor cells after treatment of TLR5 agonist, anti-PD-1 antibody or both." (PMID 38630304, 2024). "We conducted additional experiments using the B16F10 tumor model in C57BL6 mice to validate the efficacy of TLR5 agonist and anti-PD-1 combination therapy in suppressing tumor growth." (PMID 38630304, 2024). "Based on this, we advocate exploration of TLR5 agonists as possible adjuvants in anti-tumor therapies, given their ability to raise the M1 polarization of macrophages." (PMID 38630304, 2024). "In a mouse tumor model, combination therapy with TLR5 agonist and anti-PD-1 significantly inhibited tumor growth." (PMID 38630304, 2024). "TLRs, such as TLR4/TLR5, are typically activated by bacterial components, including LPS and flagellin, to exert anti‐tumor immunity." (PMID 38888519, 2024). "While some TLRs, such as TLR2 and TLR4, have shown both promotive and suppressive effects on tumor growth, others like TLR3 and TLR5 offer promising avenues for therapeutic intervention due to their more defined roles in enhancing anti-tumor immunity." (PMID 38903515, 2024). "To deepen our understanding of the role of TLR5 activation in tumor suppression, we examined the cytotoxic impact of spleen cells on MC-38 tumor cells following treatment with TLR5 agonist and anti-PD-1." (PMID 38630304, 2024). "As a result, the TLR5 agonist augmented the anti-tumor efficacy of anti-PD-1, suggesting its potential in modulating the tumor microenvironment to enhance the anti-tumor response." (PMID 38630304, 2024). "Our findings indicate that combining TLR5 treatment with an anti-PD-1 antibody (Ab) synergistically curtails tumor growth." (PMID 38630304, 2024). "TLR5 signaling can stimulate the production of pro-inflammatory cytokines and chemokines that create a tumor-promoting microenvironment." (PMID 38903515, 2024). "This indicates that combining TLR5 agonists with anti–PD-1 magnifies the anti-tumor effectiveness of anti–PD-1." (PMID 38630304, 2024). "Consistent with previous results, Tlr5+/+ mice treated with CBLB502 (low dose) + ICT treatments resulted in 20% tumor-free mice (n = 10) (mice 2 and 4)." (PMID 36635337, 2023). "Galectin-1–expressing γδ T cells are known to suppress antigen-specific anti-tumor immunity in a TLR5-dependent manner." (PMID 36480166, 2023). "MRx0518 is a strain of Enterococcus gallinarum that induces broad and robust activation of the immune system and thus anti-tumor activity mediated by toll-like receptor 5 (TLR-5)." (PMID 37568665, 2023). "Microbiota‐mediated TLR5 signaling drives tumor expression of IL‐6, which promotes MDSC mobilization and accelerates tumor growth." (PMID 37937304, 2023). "Herein, we first showed that in vitro CBLB502, a potent activator of the NF-kB signaling pathways, was sufficient to elicit a TLR5-mediated immunogenic cytokine response in tumor cells." (PMID 36635337, 2023). "In another interesting in vivo study, the researcher demonstrated contrasting effects on tumor growth after TLR5 activation by flagellin." (PMID 37936697, 2023). "Treatment of breast cancer cells with the TLR5 agonist flagellin also reported to suppress cell proliferation and inhibiting anchorage-independent tumor growth." (PMID 37936697, 2023). "In colon cancer, TLR5 knockdown enhanced tumor growth and inhibited tumor necrosis in a xenograft mouse model of CRC." (PMID 37112730, 2023). "It was included in the presented experiments due to its prior efficacy in other tumor models tested in our lab and that many cancers upregulate toll-like receptor 5 (TLR5)." (PMID 37628585, 2023). "flaB binds to Toll-like receptor 5 (TLR5) on the membrane surface of macrophages to induce the corresponding immune response for tumor therapy." (PMID 36903458, 2023).
tumor (continued). "CTP enhances the levels of TLR4 and TLR5 in ApcMin/+ mice, indicating an enhanced tumor killing response mediated by T cells." (PMID 35662701, 2022). "Attributed to the immunostimulatory effect of TLR5 signaling activation, tumor necrosis increased, leading to significant tumor regression." (PMID 35719331, 2022). "Recently, protein-based TLR5 agonists have been investigated pre-clinically: in combination with a tumor vaccine, incorporated into the adoptive cell therapy, or used alone." (PMID 36479129, 2022). "Cisplatin and Flagellin (a specific agonist of TLR5) were utilized as a positive control of tumor killing." (PMID 35210436, 2022). "The mechanism by which PA-MSHA functions is by specifically triggering the TLR5/NF-κB signal pathway in antigen-presenting cells and consequently stimulating an immune response to a tumor." (PMID 36344505, 2022). "PA-MSHA significantly increased anti-tumor immunity through polarization of macrophages toward the M1 phenotype by activating NF-κB /TLR5 pathway." (PMID 36344505, 2022). "FlaB mediates immune response through activation of TLR5-positive immune cells to a tumor in the host." (PMID 36109710, 2022). "Further, co-administration of TLR5 agonist flagellin-adjuvanted tumor-specific peptide vaccination (FlaB-Vax) with anti-PD-1 mAb inhibited melanoma tumor growth in B16-F10 cell bearing mice." (PMID 34980128, 2022). "Previous research conducted recent years used flagellin in the development of tumor vaccines, and one such study demonstrated enhanced tumor-specific CD8 + T cell-mediated immune responses after TLR5 stimulation in a therapeutic cancer vaccine model." (PMID 35669451, 2022). "In a therapeutic cancer vaccine model, flagellin was shown to improve the response of tumor-specific CD8+ T cells after TLR5 stimulation." (PMID 35680568, 2022). "On this basis, CD160, MMP-9, PTGDS, SLC26A8, and TLR5 were selected as indicators of tumor detection." (PMID 36733384, 2022). "The results showed that the uptake of 125I-VEGF in TLR5+ 4T1 tumor was significantly lower than that in TLR5− 4T1 tumor, which was also consistent with the imaging results." (PMID 34336694, 2021). "Compared with 4T1 TLR5− tumors, higher radioactivity uptake was detected in 4T1 TLR5+ tumor at all checked time points." (PMID 34336694, 2021). "Other studies showed microbiota-induced activation of TLR4 and TLR7 resulting in pro-tumorigenic immunosuppressive TME in early and progredient tumor stages TLR5 has been described to be upregulated in TME macrophages, and to be related to tumor growth." (PMID 34298645, 2021). "Biodistribution study demonstrated a higher tumor uptake of 125I-anti-TLR5 mAb in TLR5+ group compared with that in TLR5− group (P < 0.05), whereas tumor uptake of 125I-VEGF in TLR5+ group was lower than that in the TLR5− group (P < 0.05)." (PMID 34336694, 2021). "The %ID/g in TLR5+ 4T1 and TLR5− 4T1 tumor was 2.32 and 5.50, respectively (P < 0.05), and T/NT ratio was 2.85 and 4.18, respectively(P < 0.05)." (PMID 34336694, 2021). "Semi-quantitative analysis of DLU/mm2 about the tumor radioactivity showed 23982.9 for 4T1 TLR5+ tumor, whereas only 14482.9 for TLR5− tumor (P < 0.01)." (PMID 34336694, 2021). "There was no obvious radioactivity accumulation in the tumor in 125I-IgG group at all checked time points, suggesting that there was a specific accumulation of 125I-anti-TLR5 mAb in the 4T1 tumor (P < 0.01)." (PMID 34336694, 2021). "Higher radioactivity uptake was detected in 4T1 TLR5− tumor compared with that in 4T1 TLR5+ tumors at all checked time points." (PMID 34336694, 2021). "Both in vitro and in vivo experiments have shown that TLR2 and TLR5 were highly expressed in tumor-infiltrating microglia and possessed antitumor activity." (PMID 34715891, 2021). "MVD (microvessel density) count in the same slide indicated that there were much more blood vessels in 4T1 TLR5− tumor than that in TLR5+ tumor (12.8 vs 7.4; P < 0.0001)." (PMID 34336694, 2021).